CCNI2 (cyclin I family member 2)
Synonyms: FLJ16793
Tractability: PROTAC: ubiquitination databases record sites on it.
Gene: Protein-coding gene on chromosome 5 (132,747,319 to 132,754,403, forward strand). Ensembl gene ENSG00000205089.
Subcellular location (Human Protein Atlas): Cytosol; Nucleoplasm; Golgi apparatus
Gene Ontology:
Molecular function: cyclin-dependent protein serine/threonine kinase regulator activity
Cellular component: cyclin-dependent protein kinase holoenzyme complex
Genetic constraint (gnomAD): Loss-of-function variants: 34 observed, 31.2 expected, observed/expected ratio (o/e) 1.09, 90% interval 0.83 to 1.45. The synonymous counts are far from expectation, so gnomAD's model fits this gene poorly and the ratio says little. Missense variants: 452 observed, 402.96 expected, observed/expected ratio (o/e) 1.12, 90% interval 1.04 to 1.21. Synonymous variants: 231 observed, 179.23 expected, observed/expected ratio (o/e) 1.29, 90% interval 1.16 to 1.44.
Homologues: Orthologues: chimpanzee CCNI2 (99% identical), macaque CCNI2 (93% identical), rabbit CCNI2 (60% identical), dog CCNI2 (56% identical), tropical clawed frog ccni2 (33% identical), zebrafish ccni2 (32% identical), Caenorhabditis elegans cye-1 (15% identical), Drosophila melanogaster CycA (15% identical), Drosophila melanogaster CycB (14% identical), Drosophila melanogaster CycD (14% identical), Caenorhabditis elegans cyb-1 (14% identical), Drosophila melanogaster CycE (13% identical), and 6 more. Paralogues in human: CCNI (31% identical), CCNG2 (19% identical), CCNG1 (17% identical), CCNA2 (17% identical), CCNB3 (17% identical), CCNB1 (17% identical), CCNB2 (16% identical), CCNE2 (16% identical), CCNA1 (15% identical), CCNE1 (14% identical), CCNF (14% identical), CCND3 (14% identical), and 6 more.
Diseases named in the same sentence as CCNI2 in open-access papers:
CCNI2 is named in the same sentence as 9 diseases in open-access papers, as found by Europe PMC text mining. Sharing a sentence is not in itself a finding about the gene and the disease. The quoted sentences say what the papers report.
gastric cancer (1 paper, 2021). A primary or metastatic malignant neoplasm involving the stomach. "Collectively, CCNI2 was abundantly expressed in gastric cancer and positively correlated with pathological stage." (PMID 34895232, 2021). "We found that CCNI2 was abundantly expressed in gastric cancer and was positively correlated with pathological stage." (PMID 34895232, 2021). "In vitro and in vivo loss-of-function assays were performed in BGC-823 and SGC-7901 cells to explore the role of CCNI2 in gastric cancer." (PMID 34895232, 2021). "Knockdown of CCNI2 slowed down the malignant progression of gastric cancer by inhibiting tumor cell proliferation, increasing the susceptibility to apoptosis and suppressing migration." (PMID 34895232, 2021). "To explore the role of CCNI2 in gastric cancer, we determined the effect of CCNI2 downregulation on tumor biological behaviors including proliferation, colony formation, apoptosis, and migration." (PMID 34895232, 2021). "On this basis, the alterations in key apoptotic factors after CCNI2 knockdown were consistent with the apoptotic phenotypes of gastric cancer cells." (PMID 34895232, 2021). "The potential mechanism of CCNI2 regulating gastric cancer was preliminarily determined by RNA sequencing." (PMID 34895232, 2021). "In order to clarify the role of CCNI2 in gastric cancer, its potential mechanism was initially explored." (PMID 34895232, 2021). "To investigate the significance of CCNI2 expression in gastric cancer, we analyzed the correlations of CCNI2 levels with different clinicopathological characteristics." (PMID 34895232, 2021). "Altogether, our data revealed the promotive role of CCNI2 in the progression of gastric cancer and drew further interest regarding its clinical application as a potential therapeutic target." (PMID 34895232, 2021). "A major breakthrough of this study is the identification of promoting effect of CCNI2 in human gastric cancer." (PMID 34895232, 2021). "The correlation between the expression level of CCNI2 in gastric cancer tissues and clinical prognosis was analyzed." (PMID 34895232, 2021). "Based on The Cancer Genome Atlas (TCGA) database of 407 gastric cancer samples for expression profile analysis, we found that the expression level of CCNI2 in tumors was significantly higher than that of normal samples." (PMID 34895232, 2021). "The expression profile of CCNI2 in gastric cancer was determined based on The Cancer Genome Atlas (TCGA) database and immunohistochemical staining." (PMID 34895232, 2021). "The effects of altered CCNI2 expression on the biological phenotypes such as proliferation, clone formation, apoptosis and migration of gastric cancer cell lines BGC-823 and SGC-7901 were investigated." (PMID 34895232, 2021). "CCNI2 promoted the progression of human gastric cancer through HDGF, which drew further interest regarding its clinical application as a potential therapeutic target." (PMID 34895232, 2021). "CCNI2 was abundantly expressed in gastric cancer and was positively correlated with pathological stage." (PMID 34895232, 2021). "In this study, CCNI2 expression levels in gastric cancer were predicted in the database and further confirmed by immunohistochemical staining." (PMID 34895232, 2021). "We first determined the effect of CCNI2 on tumor cell proliferation, suggesting that decrease of CCNI2 expression resulted in reduced proliferation of gastric cancer cells BGC-823 and SGC-7901." (PMID 34895232, 2021). "Knockdown of CCNI2 alleviated the promoting effects of HDGF overexpression in gastric cancer cells." (PMID 34895232, 2021). "Moreover, the potential downstream mechanism of CCNI2 regulating gastric cancer was initially identified through gene microarray." (PMID 34895232, 2021). "Gastric cancer cells with reduced CCNI2 expression produced smaller colonies and reduced numbers." (PMID 34895232, 2021). "Moreover, downregulation of CCNI2 attenuated the ability of gastric cancer cells to form tumors in mice." (PMID 34895232, 2021).
gastric cancer (continued). "However, the molecular mechanism that CCNI2 regulated apoptosis in gastric cancer need more exploration." (PMID 34895232, 2021). "Additionally, inhibition of CCNI2 can slow down the malignant progression of gastric cancer by inhibiting tumor cell proliferation, increasing the susceptibility to apoptosis and suppressing migration." (PMID 34895232, 2021). "Therefore, the present study investigated the role of CCNI2 in the regulation of gastric cancer on proliferation, apoptosis, migration and tumorigenesis, as well as its underlying mechanisms." (PMID 34895232, 2021). "Besides, knockdown of CCNI2 could alleviate the promoting role of HDGF overexpression in gastric cancer cells." (PMID 34895232, 2021). "Therefore, we preliminarily determined that HDGF was regulated by CCNI2 in gastric cancer and may be a downstream target of CCNI2." (PMID 34895232, 2021). "Additionally, we studied the regulation mechanism of CCNI2 on gastric cancer and found that HDGF may be the downstream of CCNI2." (PMID 34895232, 2021). "Since there was a relationship between CCNI2 and HDGF, their biological functions in gastric cancer cell lines deserved further investigation." (PMID 34895232, 2021). "In this study, western blot analysis found that CCNI2 knockdown resulted in reduced AKT phosphorylation level, downregulated CCND1 and CDK1, upregulated MAPK9 expression in gastric cancer cells." (PMID 34895232, 2021). "Thus, CCNI2 promote the development and progression of gastric cancer through HDGF, which may be a therapeutic target for gastric cancer." (PMID 34895232, 2021).
lentivirus infection (1 paper, 2021). Virus diseases caused by the Lentivirus genus. "There were three shRNAs of CCNI2 used in this study and shCCNI2 s were infected into CRC cell lines HCT 116 and RKO with lentivirus infection technique." (PMID 33620152, 2021).
pancreatic cancer (1 paper, 2024). "Collectively, these findings demonstrate that CCNI2 was highly expressed in pancreatic cancer and was associated with poor prognosis." (PMID 37540586, 2024). "To explore the factors that influence the prognosis of this disease, we targeted the role of CCNI2, a cycle-associated protein, in pancreatic cancer." (PMID 37540586, 2024). "The biological effects of CCNI2 in human pancreatic cancer cells PANC-1 and SW1990 were determined through a series of in vitro loss/gain-of-function experiments." (PMID 37540586, 2024). "CCNI2 promoted pancreatic cancer through PI3K/protein kinase B (AKT) signaling pathway, indicating its potential as a prognostic marker and therapeutic target for pancreatic cancer." (PMID 37540586, 2024). "Although in vitro experiments have shown that CCNI2 contributes to the malignant phenotypes of pancreatic cancer cells, further investigation is needed to explore its role in vivo." (PMID 37540586, 2024). "Functionally, CCNI2 contributed to the malignant progression of pancreatic cancer by promoting the proliferation and migration of tumor cells." (PMID 37540586, 2024). "This study demonstrates that knockdown/overexpression of CCNI2 in pancreatic cancer cells can downregulate/upregulate the expression of CDK5 and CDK6." (PMID 37540586, 2024). "Our data revealed that CCNI2 expression was abnormally elevated in pancreatic cancer, and clinically, increased CCNI2 expression generally correlated with reduced overall survival." (PMID 37540586, 2024). "Meanwhile, a log-rank test was used to examine the difference in overall survival of pancreatic cancer patients between high and low CCNI2 expression groups, based on data from the TCGA database." (PMID 37540586, 2024). "Firstly, the expression of CCNI2 in normal pancreatic tissue and pancreatic cancer tissues was analyzed using The Cancer Genome Atlas (TCGA) database, which indicated that CCNI2 was upregulated in pancreatic cancer." (PMID 37540586, 2024). "Subsequently, the correlation between CCNI2 expression and the pathological features of pancreatic cancer was analyzed through clinical information." (PMID 37540586, 2024). "Conversely, the apoptosis rate of pancreatic cancer cells decreased after CCNI2 overexpression (P < 0.01)." (PMID 37540586, 2024). "Consistently, a Pearson correlation analysis further established a significant correlation between CCNI2 expression and pathological characteristics of pancreatic cancer, such as pathological grade and pathological stage." (PMID 37540586, 2024). "The biological role of CCNI2 in pancreatic cancer cells was further assessed using both in vitro and in vivo loss/gain-of-function assays." (PMID 37540586, 2024). "Our data indicate that CCNI2 has an effect on the cell cycle progression of pancreatic cancer cells." (PMID 37540586, 2024). "The present study found that the knockdown of CCNI2 promoted apoptosis in pancreatic cancer cells by activating the expression of pro-apoptotic proteins." (PMID 37540586, 2024). "Firstly, the expression of CCNI2 in pancreatic cancer tissues was determined through immunohistochemical staining." (PMID 37540586, 2024). "Our data indicated that the expression of CCNI2 was significantly higher in pancreatic cancer tissues than in adjacent normal tissues (P < 0.001)." (PMID 37540586, 2024). "The abnormally high expression of CCNI2 in pancreatic cancer holds clinical value in predicting a poor prognosis." (PMID 37540586, 2024). "Consistently, in vivo experiments verified that CCNI2 knockdown impaired the tumorigenic ability of pancreatic cancer cells." (PMID 37540586, 2024). "Consistently, the clinical relevance of CCNI2 in the human pancreatic cancer was verified through a Kaplan–Meier survival analysis, suggesting that higher expression of CCNI2 is indicative of a worse prognosis (P ═ 0.011)." (PMID 37540586, 2024). "Our data identified abnormally high expression of CCNI2 in human pancreatic cancer." (PMID 37540586, 2024).
pancreatic cancer (continued). "Moreover, our data indicated that CCNI2 had an effect on the cell cycle progression of pancreatic cancer cells." (PMID 37540586, 2024). "Considering the important role of CCNI2 in cell cycle regulation and tumor cells, we were interested in determining whether CCNI2 plays a specific key role in pancreatic cancer." (PMID 37540586, 2024). "Consequently, the established upregulation of CCNI2 in pancreatic cancer highlights its potential as a prognostic marker and therapeutic target for this disease." (PMID 37540586, 2024). "Furthermore, the effects of CCNI2 knockdown and overexpression on apoptosis of pancreatic cancer cells were analyzed by flow cytometry with Annexin V staining." (PMID 37540586, 2024). "Moreover, inhibition of this pathway partially mitigates the proliferative (promoting) and apoptotic (inhibiting) effects of CCNI2 in pancreatic cancer cells." (PMID 37540586, 2024). "In this study, the knockdown of CCNI2 led to the upregulation of MAPK9 in pancreatic cancer cells." (PMID 37540586, 2024). "Although the exact mechanism is still unclear, preliminary findings suggest that CCNI2 may regulate pancreatic cancer through the PI3K/AKT signaling pathway." (PMID 37540586, 2024). "Additionally, the phosphorylation levels of AKT and PI3K in pancreatic cancer cells overexpressing CCNI2 were increased, and treatment with a PI3K inhibitor partially reversed this effect." (PMID 37540586, 2024). "Therefore, CCNI2 was found to be necessary for the proliferation, apoptosis, and cell cycle progression of pancreatic cancer cells." (PMID 37540586, 2024). "Furthermore, the migration ability of pancreatic cancer cells in response to alterations in CCNI2 expression was examined." (PMID 37540586, 2024). "Firstly, the correlation between CCNI2 expression and pancreatic cancer was analyzed." (PMID 37540586, 2024). "Additionally, the levels of AKT and PI3K phosphorylation are increased in pancreatic cancer cells that overexpress CCNI2, and treating these cells with a PI3K inhibitor can partially reverse this effect." (PMID 37540586, 2024). "Furthermore, treatment with a PI3K inhibitor attenuated the promotion of CCNI2 overexpression on pancreatic cancer cells." (PMID 37540586, 2024). "As a result, CCNI2 may serve as a prognostic marker and potential therapeutic target for pancreatic cancer." (PMID 37540586, 2024). "Therefore, we explored the role of CCNI2 in pancreatic cancer progression to provide a theoretical basis for the treatment of this disease." (PMID 37540586, 2024). "In this study, we attempt to explore the role of CCNI2 in the progression of pancreatic cancer." (PMID 37540586, 2024). "Furthermore, our results demonstrated significant inhibition of malignant behaviors in CCNI2 knockdown pancreatic cancer cells." (PMID 37540586, 2024). "Therefore, it can be inferred that CCNI2 may regulate the proliferation and apoptosis of pancreatic cancer through the PI3K/AKT signaling pathway." (PMID 37540586, 2024). "Moreover, CCNI2 plays a crucial role in promoting the proliferation, apoptosis, cell cycle progression, and migration of tumor cells, thereby driving the progression of pancreatic cancer." (PMID 37540586, 2024). "Moreover, the promotive role of CCNI2 in pancreatic cancer was assessed both in vitro and in vivo." (PMID 37540586, 2024). "Moreover, pancreatic cancer patients with high CCNI2 expression usually had a shorter survival time, which may be an indicator of poor prognosis." (PMID 37540586, 2024). "Moreover, compared with the control group, more cells in the CCNI2 overexpression group were stained, indicating that the CCNI2 overexpression could promote the migration of pancreatic cancer cells (P < 0.001)." (PMID 37540586, 2024). "Moreover, the addition of phosphatidylinositol 3-kinase (PI3K) inhibitors could partially reverse the promoting effect of CCNI2 on the malignant phenotypes of pancreatic cancer cells." (PMID 37540586, 2024).
pancreatic cancer (continued). "Therefore, we speculate that the knockdown of CCNI2 promotes the apoptosis process in pancreatic cancer cells through a series of cascades involving apoptosis-related proteins." (PMID 37540586, 2024). "Through co-immunoprecipitation (Co-IP), we found evidence of a protein interaction between CCNI2 and CDK5/6 in pancreatic cancer cells." (PMID 37540586, 2024). "This study aims to explore the role of cyclin I-like protein (CCNI2), a homolog of cyclin I (CCNI), in the progression of pancreatic cancer, thereby providing a theoretical basis for its treatment." (PMID 37540586, 2024). "High expression of CCNI2 was observed in 10 out of 32 cases of low-grade pancreatic cancer (WHO I-II; 31.25%) and in 20 out of 29 cases of high-grade pancreatic cancer (WHO III; 68.97%) (P ═ 0.007)." (PMID 37540586, 2024).
tumor (3 papers, 2021 to 2024). "Overall, the reduction of CCNI2 expression impaired tumor formation in mice, confirming the validity of the in vitro study findings." (PMID 37540586, 2024). "High expression of CCNI2 was observed in 43 of 93 tumor tissue (46.2%) and in 0 of 101 normal tissues." (PMID 34895232, 2021). "Consistently, the representative images of immunohistochemical staining showed that the signal intensity of CCNI2 was markedly higher in tumor tissues than in normal tissues." (PMID 34895232, 2021). "The fluorescence intensity of shCCNI2 group was obviously weaker than that of shCtrl group, suggesting that CCNI2 knockdown inhibited tumor growth." (PMID 34895232, 2021). "In addition, Spearman rank correlation analysis further indicated that as the malignant degree of the tumor deepened, the expression of CCNI2 increased." (PMID 34895232, 2021). "The various indexes of solid tumor in mice models indicated that CCNI2 knockdown could suppress the growth of CRC tumor." (PMID 33620152, 2021). "Therefore, inhibition of CCNI2 repressed tumor growth in the mouse xenograft model." (PMID 34895232, 2021). "Meanwhile, statistical analysis of the correlation between CCNI2 expression and tumor characteristics in patients with CRC and Spearman rank correlation analysis also showed that there was a positive correlation between CCNI2 expression and the pathological grading of CRC." (PMID 33620152, 2021).
cardiovascular disease (1 paper, 2022). "On the contrary, FERMT1 and CCNI2 have no direct link with any form of cardiovascular disease so far although they may have some unknown functions in AF." (PMID 36078037, 2022).
infection (1 paper, 2021). The state of being infected such as from the introduction of a foreign agent such as serum, vaccine, antigenic substance or organism. "Combined with the expression of CCNI2 in RKO cells after shCCNI2 s infection, shCCNI2‐2 was used for the following study." (PMID 33620152, 2021).
CCNI2 also shares sentences with these, for which no sentence is quoted: cancer (1 paper); colorectal cancer (1); ovarian carcinoma (1).